FOXP3 (forkhead box P3)
Diseases named in the same sentence as FOXP3 in open-access papers (continued):
Sharing a sentence is not in itself a finding about the gene and the disease.
tumor (continued). "Finally, intratumoral injection of a combination of lactate signaling pathway inhibitors gallein and ARC in 4T1 tumor mouse models, led to significant reduction in the percentage of intratumoral FoxP3+ CD4+ T cells, thus confirming the role of lactate in enhancing Treg induction." (PMID 31440253, 2019). "However, others such as neutrophils, FoxP3+ve regulatory T cells (T regs) and myeloid derived suppressor cells (MDSCs) are entirely recruited from the circulation in response to factors secreted by the tumor itself or surrounding immune cells." (PMID 31824850, 2019). "In fact, the high infiltration of Foxp3 Tregs may inhibit the protumoral effects of inflammatory immune cells and may function as favorable prognostic markers at some tumor sites, whereas at other tumor sites, Treg infiltration may be linked to poor OS due to their conventional regulatory function." (PMID 31510065, 2019). "Moreover, Nrp1 deficiency on Foxp3+ Treg cells has been associated with lack of immune suppression, predominantly affecting tumor growth and worsening EAE severity." (PMID 31068948, 2019). "Indeed, CD25+ T cell depletion by means of a specific monoclonal antibody, or the inducible genetic ablation of Foxp3+ Tregs, could evoke anti-tumor immunity that controlled tumor growth." (PMID 31507585, 2019). "Thus, the present review highlighted research history, dual roles of FOXP proteins as a tumor suppressor or an oncogene, their molecular networks with other proteins and noncoding RNAs, cellular immunotherapy targeting FOXP3, and clinical implications in cancer progression." (PMID 31815635, 2019). "High quantity of tumor-infiltrating FOXP3+ regulatory T cells or PD-L1 expression on tumor cells independently predict better prognosis, suggesting that inhibitory immunomodulation might suppress lymphoma cells, as well as immune cells related with antitumor immune response." (PMID 30931288, 2019). "Moreover, these FOXP3+ lymphocytes were located in the vicinity of IL-33-expressing tumor cells." (PMID 31165767, 2019). "For example, higher frequencies of CD8 tumor infiltrating T cells are associated with improved clinical outcome and survival, but the presence of T regulatory cells (CD4+ FoxP3+) in tumor tissues is associated with reduced survival and high death hazard in patients with ovarian carcinoma." (PMID 29968076, 2018). "Therefore, using dual staining and co-localization of markers such as CD4 and Foxp3 could clarify the role of Treg TIL subset in the tumor microenvironment more accurately." (PMID 30460193, 2018). "Thus, naturally occurring Foxp3+ T-regs may be induced to migrate from the peripheral blood to the tumor sites by the chemokines CCL17, CCL22, and CCL5 and then increase in number by tumor-related factors to create a favorable environment for tumor growth." (PMID 29772686, 2018). "Neither tumor CD4 content nor FOXP3 content was associated with DDFS." (PMID 29482642, 2018). "Therefore, the targeting of FOXP3 in T-ALL might not only affect the proliferation of tumor cells but also improve the immunosuppressive status of the patients with T-ALL." (PMID 30103821, 2018). "Moreover, literature data demonstrate that tumor infiltration by Foxp3+ Tregs is not always associated with a poor prognosis, but, on the contrary, can be associated with an improved prognosis in some cancer types." (PMID 28669079, 2018). "However, no clear evidence exists for the effective decrease of Tregs in the tumor microenvironment from the limited indirect data assessing intra-tumor FoxP3 expression, and the anti-tumor efficacy appeared unsatisfactory in many previous studies with no apparent survival benefit." (PMID 30359281, 2018). "To explore the immunological mechanisms underlying the enhanced tumor-specific immune response, we assessed the effects of combination therapy on the proportions of MDSCs (CD11b+Gr1+), M2 macrophages (CD11b+F4/80+CD206+ cells), and Tregs (CD4+CD25+FoxP3+ cells) in splenocytes." (PMID 29967612, 2018).
tumor (continued). "Moreover, PRP reduced Foxp3 and Stat3 expression in peritoneal cells from H22 tumor-bearing mice." (PMID 29735884, 2018). "Indeed, tumor-bearing Senp3+/+Foxp3-Cre mice treated with NAC displayed reduced tumor size." (PMID 30089837, 2018). "Overall, the maturation of DCs by PSPEI-PAA nanocomplex has activated the CD3+CD8+ cytotoxic T cells for the tumor killing and due to unknown reasons the CD3+CD4+FOXP3+ Treg cell population were affected by the PSPEI-PAA nanocomplex administration in the B16F10 tumor mice." (PMID 30960988, 2018). "On the same note, FOXP3 expression in cancer cells might represent a tumor escape mechanism." (PMID 30103821, 2018). "Therefore, the idea that cytoplasmic localization induces the loss of the tumor-suppressive property of FOXP3 is not sufficient to explain why the tumor-suppressive function of FOXP3 is lost in wild-type FOXP3-positive tumors." (PMID 29549328, 2018). "However, the clinical implications of immunosuppressive processes related to immunologic checkpoints (PD-L1, CD8, and Foxp3) in tumors or immune cells in the tumor microenvironment remain controversial, and the potential use of these checkpoints as prognostic markers requires further study." (PMID 29025424, 2017). "Moreover, a population of CD4+/CD25-/FOXP3+ T cells was identified at the tumor site of human B-NHLs, suggesting that chronic stimulation of T cells might alter T cell differentiation and FOXP3 expression, independently of CD25." (PMID 29340116, 2017). "The polymorphisms may affect the expression of gene, and, in this context, AC haplotype may be related with higher FOXP3 expression, possibly explaining the correlation with better prognosis, since this transcription factor is considered a BC tumor suppressor gene." (PMID 28713192, 2017). "Furthermore, this relationship may be an indirect evidence of the TAM role in programming the immunomodulatory function of FoxP3+ lymphocytes within the tumor stroma, which is also reported by other authors." (PMID 28343267, 2017). "Likewise, our results also showed that FOXP3 induction in tumor-CD8+ Treg cells is TGFβ-dependent." (PMID 28487507, 2017). "This could be a compensatory response to the increase in the conventional and CD8+ T-cell populations, as the tumours of the treated animals with the highest numbers of CD4+FoxP3+ cells also exhibited the highest numbers of the conventional CD4+FoxP3− T cells and CD8+ cells." (PMID 28194010, 2017). "Interestingly, partial tumor-associated pDCs cause selective suppression of IFN-I production and possess the unique capacity to sustain the expansion of FoxP3+ Treg cells, which may contribute to breast cancer progression." (PMID 29085361, 2017). "Thus, there is a strong tendency to believe FOXP3 as a potential tumor suppressor in HCC." (PMID 28903735, 2017). "In addition, this inhibitory effect of CD8+ lymphocytes may be related to the presence of more Foxp3+ lymphocytes in the tumour microenvironment of recurrent NPC23." (PMID 28871094, 2017). "Thus we speculate that tumor FOXP3 may be a confounding factor to affect the prognostic value in NSCLC." (PMID 28716029, 2017). "In addition, the tumor inhibition of FOXP3 might be regulated by TGF-β signaling pathway via Smad2/3." (PMID 28903735, 2017). "To test this hypothesis, we developed a mouse model inoculated with HPV-carrying cancer cell lines and examined the in vitro and in vivo effects of exendin-4 on tumor growth and associated changes in the population of CD8+ CTL and Foxp3 Tregs and pro-inflammatory cytokines." (PMID 28496193, 2017). "However, we found a correlation between tumor FOXP3 expression and Treg cell counts." (PMID 28716029, 2017). "However, FoxP3+ Tregs shows its anti-tumor effect in several cancers." (PMID 29088871, 2017).
tumor (continued). "Thus, appropriate interventions to inhibit CD4+CD25+FOXP3+ Treg elevation could aid in preventing tumour progression, and regular monitoring of Treg cells in clinical patients may help to establish their prognosis." (PMID 28253320, 2017). "Moreover, FOXP3 expression in tumor cells could be an independent strong prognostic factor for distant metastasis in BC." (PMID 28713192, 2017). "In addition, we could find that the number of Treg cells expressing CD4, CD25, and FoxP3 were decreased in tumor tissue by TSA treatment." (PMID 28489607, 2017). "Furthermore, FOXP3+ cells in the tumor-near stroma compartment was an independent negative prognostic factor for OS, emphasizing the importance of assessing the location of immune cells within the tumor microenvironment." (PMID 27463005, 2016). "Additionally, cancer cells positive for FOXP3 have been detected in several distinct types of cancer that could attenuate the unfavorable prognostic influence of the tumor-infiltrating Tregs detected by IHC." (PMID 27463005, 2016). "However, in human solid tumors such as colorectal cancer or breast carcinomas, which are often richly infiltrated with immune cells, the presence and density of FOXP3+ Treg have been reported to predict favorable outcome and a better local regional control of the tumor." (PMID 26788324, 2016). "Elucidation of specific molecular features and functions that IL-17+FoxP3+ T cells possess may reveal how this intermediate cell type influences inflammation in the tumor microenvironment, and may improve understanding of the Treg/Th17 ratio in cancer prognosis." (PMID 27784305, 2016). "We expect that inoculation of mice, prior to tumor growth, with commensals able to maintain Foxp3+ Treg cell proliferation and induce moderate levels of inflammatory signals will mediate an antitumorigenic mucosal environment that considerably impedes tumor growth." (PMID 31456935, 2016). "The anti-tumor effect conferred by B cell deficiency in all three models was associated with increased T cell and NK cell infiltration and more vigorous Th1 cytokine and cytolytic T cell responses, and in EMT-6 was also associated with decreased proliferation of CD4+FoxP3+ Tregs." (PMID 27437104, 2016). "Moreover, the percentages of tumor-infiltrating CD4 + CD25 + Foxp3 + Treg cells were also higher in the treated group than in the controls, with significant increases in the percentages of these Treg cells on days 16 (12.50 ± 1.07 and 8.38 ± 0.17%) and 24 (6.95 ± 1.17 and 2.17 ± 0.74%) (p < 0.01)." (PMID 27703219, 2016). "Moreover, our data propose a new tumor suppressor role for Foxp3 in mammary epithelial cells." (PMID 26735887, 2016). "In addition, the tumor budding-related immune microenvironment, e.g., FoxP3-positive lymphocyte infiltration, which comprises a subset of lymphocytes known to suppress the host immune response, may contribute to tumor invasiveness." (PMID 27861522, 2016). "Furthermore, these data strongly suggest that Foxp3 and Runx1 protein interaction could determine Runx1 tumor promotion transcriptional activity in mammary epithelial cells." (PMID 26735887, 2016). "While weekly CY+TLRa treatment predictably resulted in partial depletion of tumor-reactive IFNγ-secreting T-cells, such treatment also produced an even greater body wide progressive depletion of Tregs, especially intratumorally, where as early as c2d3 Foxp3+ T-cells were virtually undetectable." (PMID 27341020, 2016). "These analyses revealed that the tumours are characterized by expression of inflammatory chemokines (CCL2, CCL5, CCL7, CCL8, CCL12, CXCL9, CXCL10 and CX3CL1), reflected by an enrichment of activated Foxp3− and Foxp3+ T cells expressing T helper type 1-associated chemokine receptors." (PMID 25495686, 2015). "Thus, inhibition of FOXP3 acetylation is a promising anti-tumor strategy." (PMID 26124919, 2015).
tumor (continued). "Therefore, FOXP3 expression in tumor cells has been hypothesized to represent a favorable prognostic factor in human cancers." (PMID 26305693, 2015). "Furthermore, the number of tumor-infiltrating Foxp3+ cells increased with increasing tumor stage." (PMID 25352158, 2015). "Therefore, the infiltration of FOXP3 Tregs into tumor stroma may represent a critical factor for cancer immunity and could affect cancer progression." (PMID 26305693, 2015). "TCR clonotypes are largely distinct between Foxp3− and Foxp3+ CD4+ tumor-infiltrating T cell sub-populations, indicating that conversion does not account for intra-tumoral Treg-enrichment and supporting the hypothesis that Tregs within the tumor are thymus-derived Tregs (tTregs)." (PMID 26433463, 2015). "Besides, this finding implies that even in a definite tumor type, intratumoral FOXP3+ Tregs may possess anti-tumor activity, in addition to their tumorigenic properties." (PMID 26305693, 2015). "Moreover, because the prognostic role of FoxP3+ Treg seems to be substantially different according to tumor site, the overall pooled analysis of all types of cancer maybe highly dependent on the relative proportion of each specific type of cancer." (PMID 26462617, 2015). "Interestingly, the pixel count for Tbet+ and Foxp3+ cells positively correlated with the total tumor area occupied by immune cells (r = 0.596 and r = 0.681, respectively, p < 0.0005; Pearson), suggesting that especially the infiltration with T cells resulted in a larger immune to tumor cell ratio." (PMID 26357849, 2015). "Thus, it has been suggested that the favorable prognostic effect of FOXP3 may be due to the ability to suppress tumor-promoting inflammatory responses to gut microbes." (PMID 25906747, 2015). "However, the underlying mechanism(s) require further elucidation, particularly with respect to the possibility that FOXP3 may mediate tumor-suppressive versus tumor-promoting activities." (PMID 26305693, 2015). "Taken together, our findings suggest that if the primary tumor of stage 4 NB patients >18 months is infiltrated by FoxP3-expressing effector T or NKT cells, an effective antitumor response may take place and cooperate with standard therapy to increase survival." (PMID 26161395, 2015). "Thus, we hypothesize that the signaling pathway networks downstream of FOXP3 are critical for the complicated functions mediated by FOXP3 in tumor cells." (PMID 26305693, 2015). "Thus, the original view that FoxP3+ Tregs invariably suppress tumor immunity is oversimplified." (PMID 26462617, 2015). "Moreover, epigenetic analysis of intratumoral Tregs from human NSCLC and ovarian tumors revealed demethylation at the FoxP3 TSDR similar to that observed in murine tumor models, suggesting that tumor-infiltrating Tregs in human tumors may also be nTregs." (PMID 26217588, 2015). "Given the overall abundance of CD3+CD56+ T cells in the liver and the frequent occurrence of FOXP3 expression (up to 65%) in the tumor tissue, the FOXP3+CD3+CD56+ cells could play a substantial role in the immunosuppressive network in HCC, at least for some patients." (PMID 26437631, 2015). "Therefore, biological functions of FOXP3 in tumor cells and its significance presently remain unclear." (PMID 24877082, 2014). "Therefore, we hypothesized that CD4+IL-17+ Th17 cells might be a key link between CD4+CD25+Foxp3+Tregs and tumor growth and metastasis." (PMID 24949077, 2014). "In considering CRC grows in a septic microenvironment, researchers recently hypothesized that the favorable prognostic effect of FoxP3+ T cells may reflect their ability to preferentially suppress tumor-promoting inflammatory responses to gut microbes and Th17-cell-dependent proinflammatory." (PMID 24827118, 2014).
tumor (continued). "As FOXP3 is the most widely accepted single immunohistochemical marker for Treg and has been shown to have some prognostic value, we confirmed that FOXP3 accumulated in the nuclei of small, round mononuclear lymphocytes that were clearly distinct from tumor cells." (PMID 25191901, 2014). "However we didn't detect any Foxp3 protein in those tumor cells, suggesting that Foxp3 message detected using RT-PCR may have been due to contaminating macrophages or TRegs present in the in vivo tumor FACS-isolated sample." (PMID 25264896, 2014). "However, this idea has been challenged by recent studies showing that, high tumor infiltration by FoxP3+ T cells is not always associated with a poor prognosis." (PMID 24827118, 2014). "A dominance of CD8+ T cells over CD4+ T cells (D) was associated with high numbers of FoxP3+ (CD4+) T cells (F) while low numbers of CD8+ T cells (B) were neither associated with high numbers of HLA-DR+ macrophages (K1) nor with their tumor-related localization (K3)." (PMID 24797069, 2014). "Moreover, a high percentage of FoxP3+ tumor cells (O1) tended to correlate with higher grading (S)." (PMID 24797069, 2014). "FOXP3+ nTregs in normal tissues might have a negative effect on the anti-tumor response, thus explaining their association with worse prognosis." (PMID 24938080, 2014). "Besides, Foxp3 presentation by cancer cells itself may also allow them to evade from effector T-cell responses, resulting in a survival benefit of the tumor." (PMID 23382847, 2013). "In addition, tumor establishment may trigger production of a cocktail of factors that support increased Foxp3+ T cell proliferation and/or the conversion of conventional Foxp3−CD4+ T cells into Foxp3+ cells." (PMID 23874342, 2013). "The role of Foxp3 in human tumor cells may vary among different tumor cell types." (PMID 24179494, 2013). "To determine whether Tim-3+PD-1+ Tregs exist in human tumor tissues, we compared the expression of Foxp3 in Tim-3 single positive (Tim-3 SP), PD-1 single positive (PD-1 SP), Tim-3 and PD-1 double positive cells (DP) and Tim-3 and PD-1 double negative (DN) cells." (PMID 23526963, 2013). "It is known that Foxp3+ Treg cells could inhibit anti-tumor function of CD8+ T cells in vitro." (PMID 23587428, 2013). "This may account for our finding that cytoplasmic, unlike nuclear, FOXP3 expression in tumor cells was associated with detrimental clinical outcome." (PMID 24649219, 2013). "Importantly, a low CD8+ effector T cell number is also noted relative to the high proportion of Foxp3+ Treg cells in the peripheral blood and tumor tissue in many cancer patients suggesting active recruitment of Foxp3+ Treg cells is a key feature of many tumors." (PMID 23874336, 2013). "Therefore, it’s possible that Tim-3+ Foxp3+ CD4 T cells in tumor tissue might represent the highly activated Tregs that possess potent inhibitory activity." (PMID 23526963, 2013). "In our study, in MSI CRCs, FoxP3+ TIL density was clearly associated with less invasive tumor features, in particular with the absence of VELIPI criteria, and therefore could be indirectly associated with a better prognosis." (PMID 23613769, 2013). "However, there is already evidence that the tumor microenvironment can have a predictive role, with clinical activity of ipilimumab related to high baseline expression of the immune-related genes FoxP3 and indoleamine 2,3-dioxygenase and an increase in tumor-infiltrating lymphocytes." (PMID 23452415, 2013). "While the absolute numbers of FoxP3+ cells associated with SCC were similar to TSCC, the proportion of FoxP3+cells r to cytotoxic (CD8+) T cells was significantly increased (∼2 fold) in TSCC (TSCC 0.97±0.22 vs. SCC 0.45±0.05, p<0.05), indicating a tumor permissive environment in TSCC." (PMID 23667456, 2013).